RNU6-341P (RNA, U6 small nuclear 341, pseudogene)
Gene: Small nuclear RNA gene on chromosome 14 (58,292,293 to 58,292,388, reverse strand). Ensembl gene ENSG00000252782.
Homologues: Orthologues: chimpanzee U6 (92% identical). Paralogues in human: RNU6-189P (88% identical), RNU6-797P (88% identical), RNU6-1094P (86% identical), RNU6-1127P (86% identical), RNU6-1209P (86% identical), RNU6-1131P (85% identical), RNU6-1274P (85% identical), RNU6-242P (85% identical), RNU6-41P (85% identical), RNU6-727P (85% identical), RNU6-1022P (84% identical), RNU6-1091P (84% identical), and 1288 more.